ARHGEF5 (Rho guanine nucleotide exchange factor 5)
Description:
Guanine nucleotide exchange factor which activates Rho GTPases. Strongly activates RHOA. Also strongly activates RHOB, weakly activates RHOC and RHOG and shows no effect on RHOD, RHOV, RHOQ or RAC1 (By similarity). Involved in regulation of cell shape and actin cytoskeletal organization. Plays a role in actin organization by generating a loss of actin stress fibers and the formation of membrane ruffles and filopodia. Required for SRC-induced podosome formation (By similarity). Involved in positive regulation of immature dendritic cell migration (By similarity).
Synonyms: TIM; TIM1; GEF5; P60
Tractability: Antibody: its Gene Ontology location is reachable by antibodies, with high confidence; the Human Protein Atlas places it where antibodies can reach. PROTAC: ubiquitination databases record sites on it.
Gene: Protein-coding gene on chromosome 7 (144,355,288 to 144,380,632, forward strand). Ensembl gene ENSG00000050327.
Subcellular location: Cytoplasm; Nucleus; Cell projection, podosome
Subcellular location (Human Protein Atlas): Cytosol; Plasma membrane; Nucleoplasm
Pathways (Reactome):
Signal Transduction: CDC42 GTPase cycle; G alpha (12/13) signalling events; NRAGE signals death through JNK; RAC1 GTPase cycle; RHOA GTPase cycle; RHOB GTPase cycle; RHOC GTPase cycle; RHOG GTPase cycle
Gene Ontology:
Molecular function: guanyl-nucleotide exchange factor activity; protein binding; GTP binding
Biological process: positive regulation of Rho protein signal transduction; regulation of actin cytoskeleton organization; regulation of cytoskeleton organization; regulation of GTPase activity; regulation of small GTPase mediated signal transduction; intracellular signal transduction
Cellular component: cell periphery; cytoplasm; cytosol; nucleoplasm; nucleus; plasma membrane; podosome
Genetic constraint (gnomAD): Loss-of-function variants: 11 observed, 43.97 expected, observed/expected ratio (o/e) 0.25, 90% interval 0.16 to 0.41. The synonymous counts are far from expectation, so gnomAD's model fits this gene poorly and the ratio says little. Missense variants: 153 observed, 531.12 expected, observed/expected ratio (o/e) 0.29, 90% interval 0.25 to 0.33. Synonymous variants: 56 observed, 183.4 expected, observed/expected ratio (o/e) 0.31, 90% interval 0.25 to 0.38.
Homologues: Orthologues: chimpanzee ARHGEF5 (99% identical), macaque ARHGEF5 (93% identical), rabbit ARHGEF5 (72% identical), pig ARHGEF5 (70% identical), dog ARHGEF5 (69% identical), guinea pig ARHGEF5 (67% identical), mouse Arhgef5 (65% identical), rat Arhgef5 (65% identical), Caenorhabditis elegans ephx-1 (14% identical). Paralogues in human: ARHGEF19 (21% identical), NGEF (15% identical), ARHGEF15 (14% identical), ARHGEF26 (13% identical), ARHGEF16 (13% identical), ARHGEF35 (9% identical).
Diseases named in the same sentence as ARHGEF5 in open-access papers:
ARHGEF5 is named in the same sentence as 17 diseases in open-access papers, as found by Europe PMC text mining. Sharing a sentence is not in itself a finding about the gene and the disease. The quoted sentences say what the papers report.
lung carcinoma (3 papers, 2019 to 2024). "The two other mutations predicted as deleterious, ARHGEF5 and SMTNL2, are linked to a poor prognosis in lung cancer patients, epithelial-mesenchymal transition (EMT), and Rho-GTPase signaling." (PMID 31323891, 2019). "Furthermore, lung cancers retrieved from non-smokers tended to present a higher incidence of ARHGEF5 phosphorylation dysregulation, potentially indicating a druggable oncogenic mechanism." (PMID 38539567, 2024).
colorectal cancer (1 paper, 2016). A primary or metastatic malignant neoplasm that affects the colon or rectum. "To elucidate the role of ARHGEF5 in tumor growth from human colorectal cancer cells, we examined the effects of ARHGEF5 KD on anchorage-independent cell growth in epithelial-like HCT116 and HT29 cells as well as in mesenchymal-like SW480 and SW620 cells." (PMID 27617642, 2016). "Here we showed that ARHGEF5 has a pivotal role in malignant progression, namely the acquisition of invasive/metastatic properties and promotion of tumor growth, particularly in colorectal cancer cells that gained mesenchymal phenotypes via EMT." (PMID 27617642, 2016). "In support of this, analysis of a transcriptome data set revealed that the combination of ARHGEF5 upregulation and E-cadherin downregulation or Snail upregulation is significantly correlated with poor prognosis in patients with colorectal cancers." (PMID 27617642, 2016). "To ascertain the relevance of ARHGEF5 in cancer patients, we examined the correlation between ARHGEF5 expression and prognosis in patients with colorectal cancers." (PMID 27617642, 2016). "ARHGEF5 was necessary for the invasive and in vivo metastatic activity of human colorectal cancer HCT116 cells." (PMID 27617642, 2016). "To evaluate the role of ARHGEF5 in human cancer cells, we examined the effects of ARHGEF5 KD on invasion and metastasis in human colorectal cancer HCT116 cells with invasive and metastatic activity." (PMID 27617642, 2016). "Analysis of a transcriptome data set revealed that the combination of ARHGEF5 upregulation and E-cadherin downregulation or Snail upregulation was significantly correlated with poor prognosis in patients with colorectal cancers." (PMID 27617642, 2016). "To extend the EMT-dependent function of ARHGEF5 to human cancer patients, we investigated the correlation between ARHGEF5/EMT markers and prognosis in patients with colorectal cancers." (PMID 27617642, 2016). "ARHGEF5 KD inhibited tumor growth from mesenchymal-like colorectal cancer SW480 and SW620 cells, whereas it failed to suppress the growth of epithelial-like HCT116 and HT29 cells." (PMID 27617642, 2016). "However, ARHGEF5 was not required for tumor growth in epithelial-like human colorectal cancer HCT116 and HT29 cells, whereas the growth of mesenchymal-like SW480 and SW620 cells depended on ARHGEF5." (PMID 27617642, 2016).
ependymoma (1 paper, 2015). A WHO grade II, slow growing tumor of children and young adults, usually located intraventricularly. "However, our combined approach identified novel potential biomarker candidates in ependymoma with a known relationship to cancer: ERRB2, EGFR, TWIST1, CDK4, HDAC9, and ARHGEF5 genes." (PMID 26185765, 2015).
pancreatic cancers (1 paper, 2016). "In pancreatic cancers, however, the single ARHGEF5-High group had a significantly poorer prognosis comapred with the Others, supporting the important role of ARHGEF5 in this tumor type." (PMID 27617642, 2016).
cancer (7 papers, 2015 to 2024). A tumor composed of atypical neoplastic, often pleomorphic cells that invade other tissues. "We then addressed the molecular mechanisms underlying the ARHGEF5-dependent tumor growth from mesenchymal-like cancer cells." (PMID 27617642, 2016). "Despite its established roles in skeletal muscle, immune, and cancer cell contexts, ARHGEF5’s function during brain development remains largely unexplored." (PMID 38932934, 2024). "Our findings set the basis to further explore the role of Ephexin3/ARHGEF5 as an essential effector and signaling hub in cancer cell migration." (PMID 38003617, 2023). "Furthermore, ARHGEF5’s critical involvement in the metastatic behavior of human colorectal cancer cells (HCT116) underscores its function in cancer progression." (PMID 38932934, 2024). "We focused on Ephexin3/ARHGEF5, identified as an essential gene in multiple cancer cell types." (PMID 38003617, 2023). "ARHGEF5 formed a ternary complex with Src and phosphoinositide 3-kinase and played crucial roles in Src-induced podosome formation, which may be involved in cancer malignancy invasion." (PMID 35237299, 2022). "ARHGEF5 may serve as a potential therapeutic target of a subset of malignant tumors that have undergone EMT." (PMID 27617642, 2016). "ARHGEF5 may serve as a potential therapeutic target in a subset of malignant tumors that have undergone EMT." (PMID 27617642, 2016). "Previous studies revealed that ARHGEF5 regulates actin cytoskeletal dynamics by activating the RhoA-ROCK pathway, thereby promoting the migration and invasion of cancer cells." (PMID 38932934, 2024).
tumor (5 papers, 2016 to 2023). "An in vivo tumorigenesis assay revealed that ARHGEF5 had the potential to promote tumor growth via the phosphatidylinositol 3-kinase (PI3K) pathway." (PMID 27617642, 2016). "We previously identified ARHGEF5, a member of the Dbl family of GEFs, as a multifunctional mediator of Src-induced cell invasion and tumor growth." (PMID 27617642, 2016). "Taken together, our findings suggest that EMT-induced ARHGEF5 activation contributes to the progression of tumor malignancy." (PMID 27617642, 2016). "In these mesenchymal-like cells, Akt was activated via ARHGEF5 and its activity was required for tumor growth." (PMID 27617642, 2016). "Induction of EMT by tumor necrosis factor-α or Slug in HCT116 cells resulted in the dependence of tumor growth on ARHGEF5." (PMID 27617642, 2016). "The present study showed that ARHGEF5 is crucial for tumor growth, particularly in mesenchymal-like cells." (PMID 27617642, 2016). "Here we show that the Rho guanine nucleotide exchange factor (GEF) ARHGEF5 promotes tumor malignancy in a manner dependent on EMT status." (PMID 27617642, 2016). "Furthermore, ARHGEF5 had the potential to promote tumor proliferation via the phosphatidylinositol 3-kinase (PI3K) pathway." (PMID 35237299, 2022). "ARHGEF5 promoted tumor malignancy via epithelial-mesenchymal transition." (PMID 36241648, 2022). "We show that ARHGEF5 is functionally upregulated during EMT and promotes invasion/metastasis and tumor growth, particularly in cells that have acquired mesenchymal phenotypes." (PMID 27617642, 2016).
neurodegenerative disease (1 paper, 2024). A disorder of the central nervous system characterized by gradual and progressive loss of neural tissue and neurologic function. "ARHGEF5 plays an important role in the regulation of endogenous Rho GTPases, and aberrant regulation of Rho GTPases plays a key role in neurodegenerative diseases such as AD." (PMID 38159198, 2024).
ARHGEF5 also shares sentences with these, for which no sentence is quoted: bacterial infection (1 paper); breast carcinoma (1); colon cancer (1); conjunctivitis (1); developmental delay (1); genetic disorder (1); infection (1); Intellectual disability (1); non-small cell lung carcinoma (1); Williams-Beuren syndrome (1).